SNTG1 (syntrophin gamma 1)
Description:
Adapter protein that binds to and probably organizes the subcellular localization of a variety of proteins. May link various receptors to the actin cytoskeleton and the dystrophin glycoprotein complex (By similarity). May participate in regulating the subcellular location of diacylglycerol kinase-zeta to ensure that diacylglycerol is rapidly inactivated following receptor activation.
Synonyms: G1SYN; SYN4
Tractability: PROTAC: ubiquitination databases record sites on it.
Gene: Protein-coding gene on chromosome 8 (49,909,789 to 50,796,692, forward strand). Ensembl gene ENSG00000147481.
Subcellular location: Cytoplasm, cytoskeleton; Nucleus
Gene Ontology:
Molecular function: protein binding; structural molecule activity
Biological process: cell communication; synaptic signaling
Cellular component: cytoplasm; cytoskeleton; ruffle membrane; dystrophin-associated glycoprotein complex; plasma membrane; syntrophin complex; nucleus; synapse
Genetic constraint (gnomAD): Loss-of-function variants: 23 observed, 51.05 expected, observed/expected ratio (o/e) 0.45, 90% interval 0.32 to 0.64. The upper end of that interval is the gene's LOEUF score, 0.64, which puts it in group 2 of 6, group 1 being the genes least tolerant of losing a copy. Missense variants: 527 observed, 486.82 expected, observed/expected ratio (o/e) 1.08, 90% interval 1.01 to 1.16. Synonymous variants: 206 observed, 185.14 expected, observed/expected ratio (o/e) 1.11, 90% interval 0.99 to 1.25.
Homologues: Orthologues: chimpanzee SNTG1 (99% identical), dog SNTG1 (98% identical), pig SNTG1 (96% identical), mouse Sntg1 (93% identical), rabbit SNTG1 (93% identical), rat Sntg1 (91% identical), guinea pig SNTG1 (88% identical), tropical clawed frog sntg1 (86% identical), macaque SNTG1 (85% identical), zebrafish sntg1 (78% identical), Drosophila melanogaster Syn2 (37% identical), Caenorhabditis elegans stn-2 (32% identical). Paralogues in human: SNTG2 (51% identical), SNTA1 (26% identical), SNTB2 (24% identical), SNTB1 (23% identical).
Diseases named in the same sentence as SNTG1 in open-access papers:
SNTG1 is named in the same sentence as 21 diseases in open-access papers, as found by Europe PMC text mining. Sharing a sentence is not in itself a finding about the gene and the disease. The quoted sentences say what the papers report.
idiopathic scoliosis (3 papers, 2019 to 2022). A scoliosis with no known cause. "Mutations in SNTG1 have been found to lead to idiopathic scoliosis and increase the systolic blood pressure which may contribute to hypertension." (PMID 32915819, 2020). "The gene for syntrophin gamma 1 (SNTG1) was one of the top genes associated with more than five phenotypes for human pulmonary diseases, and it has been identified as a candidate gene for human idiopathic scoliosis." (PMID 31597369, 2019).
Alzheimer disease (2 papers, 2019 to 2023). A progressive, neurodegenerative disease characterized by loss of function and death of nerve cells in several areas of the brain leading to loss of cognitive function such as memory and language. "SNTG1 has also been implicated in obstructive sleep apnea, a condition that is highly prevalent in patients with Alzheimer’s disease." (PMID 30112632, 2019).
scoliosis (2 papers, 2010 to 2021). A congenital or acquired spinal deformity characterized by lateral curvature of the spine. "This identified 12 CNVs in four scoliosis-associated genes (TBX6, NOTCH2, DSCAM, and SNTG1) as well as eight recessive and 64 novel rare CNVs in 15 additional genes." (PMID 34440387, 2021).
benign breast disease (1 paper, 2017). "We additionally included delta-sarcoglycan (gene product of the SGCD gene) since it forms a complex with syntrophin-gamma 1 (SNTG1), and it has been only reported to be affected in benign breast disease." (PMID 29290962, 2017). "In two of these genes, α1-syntrophin (SNTA1, that forms a complex with SNTG1) and δ-sarcoglycan (SGCD), there is evidence of decreased protein expression in benign breast disease." (PMID 29290962, 2017).
breast tumor (1 paper, 2017). "Here, we report syntrophin gamma 1 (encoded by SNTG1) as a new protein down-regulated in breast tumor samples." (PMID 29290962, 2017).
Duchenne muscular dystrophy (1 paper, 2019). Duchenne muscular dystrophy (DMD) is a neuromuscular disease characterized by rapidly progressive muscle weakness and wasting due to degeneration of skeletal, smooth and cardiac muscle. "The SNTG1 gene is a cytoplasmic membrane protein that associates with the Duchenne muscular dystrophy gene, dystrophin." (PMID 31506096, 2019).
lung adenocarcinoma (1 paper, 2010). A carcinoma that arises from the lung and is characterized by the presence of malignant glandular epithelial cells. "We performed high-resolution array comparative genomic hybridization analysis of lung adenocarcinoma in sixty never smokers and identified fourteen new minimal common regions (MCR) of gain or loss, of which five contained a single gene (MOCS2, NSUN3, KHDRBS2, SNTG1 and ST18)." (PMID 21151896, 2010).
neuroblastoma (1 paper, 2016). Neuroblastoma (NB) is the most common solid, extracranial childhood tumor. "The protein product (γ-1-syntrophin) of another gene downregulated in senescence and AD, SNTG1, binds and localizes the neurotrophic peptide γ–enolase to the plasma membrane and neurite growth cones of neuroblastoma cells." (PMID 27630559, 2016).
Stroke (1 paper, 2021). Sudden impairment of blood flow to a part of the brain due to occlusion or rupture of an artery to the brain. "Of the three marginally associated intronic variants within the SNTG1 (syntrophin gamma-1) gene, rs117962542 has been previously implicated with stroke risk in a sample of ∼70,000 individuals of European descent from MEGASTROKE." (PMID 34992631, 2021).
tumor (2 papers, 2016 to 2017). "By this interpretation, the most decreased expression in tumor protein relative to healthy tissue is in ROBO1 ∼72.3%, followed by delta sarcoglycan (encoded by SGCD) ∼68.9%, and syntrophin gamma 1 (SNTG1 gene) ∼58% (SGCD)." (PMID 29290962, 2017).
SNTG1 also shares sentences with these, for which no sentence is quoted: glioblastoma (2 papers); pneumonia (2); Sepsis (2); benign meningioma (1); breast carcinoma (1); cancer (1); deafness (1); Hypertension (1); obstructive sleep apnea (1); pulmonary diseases (1); viral infection (1).